SPRED1 (sprouty related EVH1 domain containing 1)
Diseases named in the same sentence as SPRED1 in open-access papers (continued):
Sharing a sentence is not in itself a finding about the gene and the disease.
acute promyelocytic leukemia (2 papers, 2020 to 2022). An aggressive form of acute myeloid leukemia (AML), characterized by arrest of leukocyte differentiation at the promyelocyte stage, due to a specific chromosomal translocation t(15;17) in myeloid cells. "In this study, we expanded our clinical samples, collected 75 de novo AML [non-acute promyelocytic leukemia (non-APL)], and detected the methylation degree of SPRED1 and its correlation with treatment response and long-term survival." (PMID 35359401, 2022). "Non-acute promyelocytic leukemia (non-APL) patients with decreased SPRED1 had significantly lower 2-year progression-free survival and event-free survival rates." (PMID 32175275, 2020).
autoimmune disease (2 papers, 2021 to 2025). A disorder resulting from loss of function or tissue destruction of an organ or multiple organs, arising from humoral or cellular immune responses of the individual to their own tissue constituents. "Human genetic analysis has shown that SOCS family members are strongly associated with autoimmune diseases, allergies, and tumorigenesis, and SPRED1 is involved in NF1-like syndromes and tumors." (PMID 34121041, 2021). "We identified 12 pleiotropic genes, including PLCL1, SPRED1, and CNNM2, associated with the comorbidity of DeP and autoimmune diseases." (PMID 41212883, 2025).
bipolar disorder (2 papers, 2013 to 2022). A disorder of the brain that causes unusual shifts in mood, energy, activity levels and the ability to carry out day-to-day tasks. "The SNP rs11854769 was identified in a recent GWAS of bipolar disorder; this finding may indicate that this SPRED1 variant may confer a genetic predisposition for multiple neuropsychiatric diseases." (PMID 23646285, 2013).
chronic myeloid leukemia (2 papers, 2021 to 2023). "Additionally, a recent study demonstrated that SPRED1 deletion was able to augment drug resistance in chronic myeloid leukemia." (PMID 36629984, 2023).
glioma (2 papers, 2018 to 2020). A benign or malignant brain and spinal cord tumor that arises from glial cells (astrocytes, oligodendrocytes, ependymal cells). "Functional validation with CRISPR-Cas9-induced mutations in novel genes Tead2, Spred1, and Nav3 demonstrates heightened EGFRvIII-glioma cell proliferation." (PMID 32727536, 2020).
lung adenocarcinoma (2 papers, 2020 to 2023). A carcinoma that arises from the lung and is characterized by the presence of malignant glandular epithelial cells. "Since gain-of-function EGFR mutations tend to be mutually exclusive with loss-of-function SPRED1 and NF1 mutations in lung adenocarcinoma, we used oncogenic EGFR(L858R) as a model system." (PMID 32697994, 2020).
lung carcinoma (2 papers, 2017 to 2021). "This microRNA is capable of promoting lung cancer by subexpressing several regulators (SPRED1, SPRED2, SPRY1, RASA1, SPRY3 and SPRY4) in RAS / MAPK signaling, which leads to an increase in the signaling of this pathway." (PMID 29053755, 2017).
acute leukemia (1 paper, 2020). A clonal (malignant) hematopoietic disorder with an acute onset, affecting the bone marrow and the peripheral blood. "However, the association of SPRED1 expression status with the clinical features as well as the prognostic significance of SPRED1 in acute leukemia, especially adult AML, remains to be determined." (PMID 32175275, 2020).
acute lymphoblastic leukemia (1 paper, 2020). Leukemia with an acute onset, characterized by the presence of lymphoblasts in the bone marrow and the peripheral blood. "A single-nucleotide polymorphism array analysis has shown that SPRED1 deletion is frequently found in relapsed B cell acute lymphoblastic leukemia (B-ALL)." (PMID 32175275, 2020). "We determined mRNA levels of SPRED1 in the bone marrow mononuclear cells from adult patients, including 113 AMLs and 22 acute lymphoblastic leukemias (ALLs), as well as in 37 healthy control subjects." (PMID 32175275, 2020).
anemia (1 paper, 2022). A reduction in the number of red blood cells, the amount of hemoglobin, and/or the volume of packed red blood cells. "The consumption of HFD, but not LPS treatment or aging, induced ERK hyperactivation and aberrant self-renewal in Spred1-deficient HSCs, leading to the appearance of anemia and myeloproliferative neoplasm-like disease (right)." (PMID 35163498, 2022). "We demonstrated that the altered gut microbiota composition caused by HFD affected the regulation of HSC self-renewal in Spred1-deficient mice, which develop myeloproliferative neoplasm-like disease and anemia." (PMID 35163498, 2022).
asthma (1 paper, 2012). "Additionally, Spred1 has been shown to negatively regulate IL-5-induced eosnophilia in a mouse model of asthma." (PMID 23166773, 2012).
cognitive deficits (1 paper, 2021). "Furthermore, dysfunction of SPRED1, a homologous member of the SPRED protein family, causes cognitive deficits both in humans and mice, altogether possible reasons for the impaired communication in SPRED2-KOs." (PMID 34679429, 2021).
cortical dysplasia (1 paper, 2019). "As SPRED1 functions as a multidomain scaffolding protein it is not unlike other structural proteins commonly associated with cortical dysplasia; we have identified that this gene may be modulated by THs." (PMID 30874585, 2019).
endometrial adenocarcinoma (1 paper, 2023). "Moreover, a recent study indicated that SPRED1 expression was upregulated by knockdown of EZH2 in endometrial adenocarcinoma cells." (PMID 36629984, 2023).
freckles (1 paper, 2022). Disorders of increased melanin pigmentation that develop without preceding inflammatory disease. "In families with an autosomal dominant phenotype of CALM with or without freckles but without other NF1-associated disease features or a pathogenic NF1 gene variant, 19% have a mutation in the SPRED1 gene." (PMID 34928431, 2022).
hereditary cancer (1 paper, 2025). Malignant neoplasms occurring in families at a rate greater than that expected by chance and caused by germline mutations in a specific gene. "LP/P findings in pleiotropic genes linked to human development and hereditary cancer (TSC1, PHOX2B, WT1, SPRED1, NF1, LZTR1, HOXB13) were identified in several patients with syndromic phenotypes." (PMID 40060932, 2025).
Hyperglycemia (1 paper, 2021). An increased concentration of glucose in the blood. "SPRED1 gene and protein expression were not affected by hyperglycemia." (PMID 33709000, 2021).
macroencephaly (1 paper, 2012). "Interestingly, mutations in the Spred1 gene, which codify for a structural and functional protein related to Sprouty, has been identified in pathologies characterized by macroencephaly and mental retardation." (PMID 22384148, 2012).
metastatic melanoma (1 paper, 2022). A melanoma that has spread from its primary site to another anatomic site. "We also found that BRAF class 1 mutations (20.3% vs. 5.8%) were more frequent in metastatic melanomas, while SPRED1 inactivation (3.9% vs. 19.8%), SF3B1 mutations (1.6% vs. 9.3%), and amplifications of CRKL (6.3% vs. 17.4%) and MAPK1 (1.6% vs. 11.6%) were more frequent in primary samples." (PMID 35706047, 2022).
metastatic tumors (1 paper, 2019). "When comparing any aberration with respect to primary and recurrent/metastatic sample types, SF3B1 (Fisher’s exact, P = 0.0057) and SPRED1 (Fisher’s exact, P = 0.02) mutations were mostly present in primary samples and NRAS aberrations were predominantly in recurrent/metastatic tumors." (PMID 31320640, 2019).
microphthalmia (1 paper, 2024). Congenital or developmental anomaly in which the eyeballs are abnormally small. "Our previous findings using conventional germline KO mouse lines, further substantiated in this study using conditional KO lines, clearly establish that microphthalmia and the small lens phenotype intrinsic to the lens and is the direct result of Spred1/2 loss." (PMID 38391903, 2024).
Vestibular schwannoma (1 paper, 2011). A vestibular schwannoma (also known as acoustic neuroma, acoustic neurinoma, or acoustic neurilemoma) is a benign, usually slow-growing tumor that develops from the VIIIth cranial nerve supplying the inner ear. "SPRED1 mutation analysis was conducted on paraffin-embedded tissue from this vestibular schwannoma." (PMID 21089071, 2011).
viral infection (1 paper, 2020). "Many genes, such as zinc finger protein (ZFP)-148, sprout 1 (SPRY1), sprouty-related EVH1 domain-containing protein 1 (SPRED1), and E-twenty six 1/2 (ETS1/2), regulate replication in viral infection." (PMID 32754448, 2020).
tumor (33 papers, 2009 to 2026). "The SPRED1 gene is a tumor suppressor that encodes a negative regulator of MAPK signaling, previously identified as a driver in MM." (PMID 38191367, 2024). "SPRED1 has been implicated in several biological process, such as signal transduction, dysplasia and tumor development." (PMID 36629984, 2023). "Inactivating SPRED1 lesions, including biallelic deletion and frameshift changes, have also been described in this tumor type." (PMID 41514664, 2026). "In summary, our findings demonstrate that TTC36 functions as a tumor suppressor in HCC by inhibiting the Ras/MAPK signaling pathway via YBX3/SPRED1 axis." (PMID 41208883, 2025). "The TTC36/YBX3/SPRED1 axis inhibits tumor growth but induces sorafenib resistance via compensatory PI3K/Akt activation." (PMID 41208883, 2025). "Among MM drivers, somatic mutations of NRAS and the TERT promoter are reported, as well as mutually exclusive loss of function mutation of the tumor suppressors NF1 and SPRED1, the latter co-occurring with activating KIT mutations." (PMID 38191367, 2024). "We intend to continue collecting human samples to validate the expression of SPOCK2 and SPRED1 in tumor tissues." (PMID 36629984, 2023). "This mitfa promoter has been used to drive Cas9 to inactivate genes specifically in melanocytes, such as SPRED1, an important tumor suppressor in mucosal melanoma." (PMID 36538362, 2022). "Recent studies have suggested that SPRED1 is attenuated, and SPRED1 is a potential tumor suppressor in pediatric ALL or AML." (PMID 32175275, 2020). "SPRED1 is a tumor suppressor that acts by transporting NF1 to the plasma membrane where it inhibits RAS-GTP signaling." (PMID 31320640, 2019). "High level of MiR-126 induces angiogenesis in non-malignant tissues by a mechanism that involves MiR-126-induced inhibition of the tumour suppressor SPRED1." (PMID 30223817, 2018). "Studies of Spred1 expression in T cells showed that Spred-1 is highly up regulated in the tumor-infiltrating CD8+ T cells and that TGF-β modulates the infiltrating function of CD8+ T cells via TCR signaling and Spred1 expression." (PMID 19956540, 2009). "The expression levels of SPRED1 and SPRED2 in tumor tissues are lower than those in normal tissues, suggesting that the downregulation of SPRED1 and SPRED2 may serve as important indicators of tumor initiation and progression." (PMID 38402263, 2024). "Overexpression of SPOCK2 or SPRED1 significantly restrained tumor growth." (PMID 36629984, 2023). "In the cancer setting, such non-germline, mosaic F0 approaches have been very important in identifying oncogenes (i.e. SETDB1 and CRKL) and tumor suppressors (i.e. SPRED1) and can be used to test effects in thousands of animals per experiment, a major benefit of the zebrafish system." (PMID 36538362, 2022). "Analogous to NF1, around 30% of MM cases with SPRED1 inactivation simultaneously exhibit KIT alterations, suggesting that SPRED1 inactivation may be in collaboration with other oncogenic events to stimulate tumor development." (PMID 34350118, 2021). "Moreover, 16 of the top 20 CIS genes had supporting fusion transcripts from at least one tumor, including Cdkn2a, Nf1, Pten, Sox6, Sox5, Spred1, and Tcf12 (all containing PB splice acceptor fusions, implying transcript termination)." (PMID 32727536, 2020). "Although neither Spred1 nor Nav3 mutations affected tumor cell sensitivity to EGFR inhibition with afatinib, loss of Spred1 or Nav3 increased sensitivity of EGFRvIII-tumor cells to MEK inhibitor treatment with trametinib." (PMID 32727536, 2020).
tumor (continued). "These mutations may occur in receptors (e.g., KITKIT), effectors (BRAF, NRAS), or inhibitors (NF1, RASA2, CDKN2A, SPRED1) of the pathway, leading to proliferation of transformed melanocytes, abnormal differentiation, and persistent survival with impaired apoptosis of tumour cells." (PMID 41295253, 2025). "However, other genes with similar tumor suppressive function in our screen, such as Ambra1, Gpatch8, and Spred1, may be less appreciated as tumor suppressors." (PMID 38302473, 2024). "Moreover, overexpression of SPOCK2 or SPRED1 could inhibit tumoral proliferation, migration ratio, and invasion activity in vitro as well as retard tumor growth in vivo." (PMID 36629984, 2023). "These lines of evidence suggest that SPRED1 may be a tumor suppressor." (PMID 36629984, 2023). "Some of the more well described targets are SPRED1, p85β, and PI3KR2 governing vascular integrity, VEGF-A regulating AKT-pathway signaling, CXCR4 and IRS-1 involved in CRC cell proliferation and migration, and KRAS impacting on the viability of the mutated tumor cells." (PMID 35582589, 2019). "NF1 acts as a tumor suppressor by accelerating RAS GTP hydrolysis, a process facilitated by SPRED1, which recruits NF1 to the plasma membrane." (PMID 41514664, 2026). "Other regulators of tumor biology, including PTPRS, CSPG4, SPRED1, CD59, and PROCR, were all downregulated upon CBX3 knockdown." (PMID 39545414, 2024). "Next, we evaluated the expression of SPOCK2 and SPRED1 in the LUAD samples from the TCGA database, and found that the expression of SPOCK2 and SPRED1 in the tumor tissues of LUAD patients was significantly decreased." (PMID 36629984, 2023). "To elucidate the effect of SPOCK2 or SPRED1 on tumor growth of LUAD cells in vivo, we subcutaneously injected the SPOCK2 or SPRED1 overexpressed A549 cells into the nude mice." (PMID 36629984, 2023). "Further analyses showed that the overexpression of SPOCK2 or that of SPRED1 statistically inhibited LUAD cells proliferation, migration ratio, invasion activity, and tumor growth." (PMID 36629984, 2023). "The gene community containing the tumor suppressors NF1 and SPRED1 illustrates this phenomenon (Fig EV5C)." (PMID 30573688, 2018). "SPRED1, sprout-related, EVH1 domain containing protein 1, is a tumor suppressor." (PMID 34350118, 2021). "In our study, we confirmed the negative correlation between miR-196a and SPRED1 expression levels in both BC cells and BC tumor tissues." (PMID 29685157, 2018). "Sprouty and SPRED proteins are known to be negative regulators of MAPK signaling and may thus function as tumor suppressors, whereas SPRED1 and SPRED2 have been additionally found to be negative regulators of hematopoiesis." (PMID 28882895, 2017).
cancer (13 papers, 2015 to 2024). A tumor composed of atypical neoplastic, often pleomorphic cells that invade other tissues. "An increased risk of cancer was observed in SPRED1-heterozygotes in the UKBB with the elevated risk beginning in the 50s." (PMID 39802765, 2024). "Specifically, poorer survival was associated with samples that had a SPRED1 aberration in combination with another cancer driver mutation: NRAS, NF1 or KIT (log-rank test, p = 0.0074)." (PMID 33067454, 2020). "IT has been recently revealed that mutations resulting in the loss of SPRED1 function occur in ∼ 2% of human cancers, and genetic removal of SPREDs leads to various phenotypes, such as behavioral issues, dwarfism, and increased susceptibility to leukemia in mice." (PMID 38402263, 2024). "There may be an increased cancer risk for adult SPRED1 heterozygotes." (PMID 39802765, 2024). "The following IHC indicated that the PAPSS1, MAP3K11, and SPRED1 showed lower IHC score in KIRC compared with para-cancer samples." (PMID 38217548, 2024). "In UKBB, SPRED1 heterozygotes had a significantly increased cancer prevalence compared to controls (OR: 3.8; 95% CI: 2.48–8.64; p = 1.2×10−3)." (PMID 39802765, 2024). "The immunohistochemistry indicated that the PAPSS1, MAP3K11, and SPRED1 showed lower IHC score in KIRC compared with para-cancer samples." (PMID 38217548, 2024). "And the PAPSS1, MAP3K11, and SPRED1 showed lower IHC scores in KIRC compared with para-cancer samples (p<0.05)." (PMID 38217548, 2024). "In SPRED1-heterozygotes, cancer prevalence was significantly increased in UKBB (OR:3.8 [95% CI: 2.48–8.64]; p=1.2×10−3) but not in the MyCode cohort." (PMID 39802765, 2024). "SPRED1 and NF1 loss-of-function mutations occur across multiple cancer types and developmental diseases." (PMID 32697994, 2020). "We also analyzed phosphorylation on S107 and several other sites on SPRED1 in a wider panel of cancer cell lines expressing activated RTKs." (PMID 32697994, 2020). "For now, given that the excess cancer was driven by skin malignancies, it may be prudent to evaluate concerning skin findings in SPRED1-heterozygotes." (PMID 39802765, 2024). "Surprisingly, there was a significant excess of cancer risk in SPRED1-heterozygotes in UK Biobank but not MyCode." (PMID 39802765, 2024). "Their presence should raise suspicions of a potential diagnosis of CMMRD in young cancer patients or patients with suspected NF1 but without an NF1 or SPRED1 pathogenic variant." (PMID 35158896, 2022). "Furthermore, we detected phosphorylation of SPRED1 on S105 in several other cancer cell lines (PC9, U2OS, A431, and H1975)." (PMID 32697994, 2020). "A significant (p<0.05) association of the expression of GDPD3 or SPRED1 to cancer specific survival from these data was not identified by Cox proportional hazard modeling across these three datasets." (PMID 26230923, 2015). "This was only examined in NS and SPRED1 heterozygotes in UKBB, since cancer cases reported in CBL and CFC heterozygotes were too few to provide meaningful analyses." (PMID 39802765, 2024). "However, there may be an increased cancer risk for adult NSML- and SPRED1-heterozygotes." (PMID 39802765, 2024). "In MyCode, there was a small number of observations (n = 4) with a non-significant difference (p = 0.98) in cancer prevalence in SPRED1-heterozygotes." (PMID 39802765, 2024). "Thus, current work provides new insights into understanding the potential roles of EZH2-mediated SPOCK2 or SPRED1 in LUAD and their potential as biomarkers for cancer therapy and prognosis." (PMID 36629984, 2023). "It is noteworthy, however, that RNF128, SLC16A1, SPRED1, TNRC6B, and TTK are novel in that they are found only among the candidate cancer genes identified by forward genetic screens in mice or among the genes whose expression changes in cancer." (PMID 33427197, 2021).
neurodegenerative disease (2 papers, 2024 to 2025). A disorder of the central nervous system characterized by gradual and progressive loss of neural tissue and neurologic function. "Our KI mice could provide a useful tool to investigate the role of SPRED1 in neurodegenerative disease." (PMID 39510187, 2024).
SPRED1 also shares sentences with these, for which no sentence is quoted: mucosal (7 papers); cutaneous melanoma (3); Noonan syndrome (3); café au lait macules (2); gastric cancer (2); lipoma (2); neurological diseases (2); airway hyperresponsiveness (1); allergies (1); aneurysm (1); atherosclerosis (1); Atrophy (1); attention deficit-hyperactivity disorder (1); brain glioma (1); cardiofaciocutaneous syndrome (1); cerebellar ataxia (1); colorectal cancer (1); depression (1); developmental delays (1); fibrosarcoma (1); genetic disorder (1); hearing loss (1); inflammation (1); juvenile myelomonocytic leukemia (1); kidney tumors (1); learning disabilities (1); Macrocephaly (1); metastatic cancers (1); myeloid leukemia (1); neurodevelopmental disorder (1).